CASP1 (caspase 1)
Diseases named in the same sentence as CASP1 in open-access papers (continued):
Sharing a sentence is not in itself a finding about the gene and the disease.
gout (68 papers, 2013 to 2025). A condition characterized by painful swelling of the joints, which is caused by deposition of urate crystals. "NLRP3 inflammasome (NLRP3, apoptosis-associated speck-like protein (ASC), and caspase-1) signaling is involved in the pathogenesis of interleukin (IL)-1β-mediated gouty arthritis." (PMID 33935726, 2021). "The NLRP3 inflammasome, composed of NLRP3, the adaptor protein ASC, and caspase-1, is closely linked to the pathogenesis of various metabolic diseases including gouty arthritis." (PMID 27934918, 2016). "Our study mainly analyzed the expression level and function of CASP1 gene transcript variant mRNA in peripheral blood mononuclear cells of patients with gout in different TCM syndromes." (PMID 26557856, 2015). "A large number of studies have shown that cysteinyl aspartate specific protease-1 (CASP1) played an important role in the inflammatory response of primary gout, but the decreased expression of different CASP1 transcript variant could inhibit the activation of IL-1β." (PMID 26557856, 2015). "Colchicine has been demonstrated to inhibit the NLRP3 inflammasome and suppress caspase-1 activation in gout." (PMID 39792323, 2025). "Although no significant change in the expression of NLRP3 after supplementation with butyrate was observed in both the gout and peritonitis models, supplementation with butyrate effectively suppressed the production of caspase-1 and IL-1β." (PMID 39907694, 2025). "Inhibition of PI3Kγ reduces the activation of caspase-1 and the recruitment of leukocytes at inflammatory sites in acute gouty arthritis." (PMID 40606658, 2025). "In both models of gouty arthritis, osteostatin administration resulted in reduced pro-inflammatory cytokine production, decreased leukocyte migration, and reduced caspase-1 and NF-κB activation." (PMID 38474000, 2024). "Coptisine in Huanglian can be used to treat NLRP3 inflammasome-mediated gouty arthritis by inhibiting caspase-1 to block NLRP3 inflammasome activation." (PMID 38218891, 2024). "MCC950 treatment significantly alleviated NLRP3, Caspase-1 and IL-1β protein overexpression in ankle joint tissues of gout model mice compared with vehicle-treated (control) group, confirming the effectiveness of MCC950 on NLRP3 inflammasome." (PMID 37464384, 2023). "Lee’s study showed that oral administration of caffeic acid phenethyl ester (CAPE) suppressed monosodium urate (MSU) crystal-induced caspase-1 activation and IL-1β production in mouse gouty arthritis models." (PMID 37834377, 2023). "Here, our results indicated that EA remarkably decreased NLRP3 inflammasome components’ overexpression, including NLRP3, Caspase-1 and IL-1β of gout model animals." (PMID 37464384, 2023). "Given that NLRP3 inflammasome activation is a hallmark of AGA, we examined the levels of IL-1β, caspase-1, and NLRP3 in each group of the spontaneous gout rat model." (PMID 36686377, 2023). "ELISA analysis showed that the gout group significantly up-regulated the levels of IL-1β, Caspase-1, IL-6 and TNF-α, and significantly decreased the levels of IL-10, which were induced by MSU (p < 0.05)." (PMID 36313318, 2022). "In vivo and in vitro studies, Z1456467176 inhibited ATP- or BzATP-induced P2X7R activation to block the NLRP3-caspase-1-IL-1β pathway, alleviating the clinical manifestations of gouty arthritis and confirming P2X7R as an effective therapeutic target." (PMID 36052144, 2022). "At the onset of gouty arthritis, MSU is involved in caspase-1 activation, which causes the production of interleukin-1β (IL-1β) and interleukin-18 (IL-18), inducing proinflammatory responses." (PMID 36297105, 2022). "It has been reported that the activity of neutrophil-derived proteases plays a more dominant role in the acute inflammation induced by IL-1β in the gout context, suggesting that caspase-1 plays a minor role." (PMID 36496970, 2022).
gout (continued). "NLRP3 and IL-1β have been identified as risk factors for gout, and it has been clinically confirmed that high levels of NLRP3, Caspase-1, IL-1β and IL-6 have been detected in serum and synovial fluid of patients." (PMID 36313318, 2022). "Previous studies revealed that the NOD-like receptor signaling pathway, especially the NLRP3 inflammasome, plays an important role in the pathogenesis of AGA; therefore, we mainly investigated the effect of PEL on the NLRP3/ASC/caspase-1 pathway in gout rats." (PMID 35449811, 2022). "In continuation with our previous work, the present study demonstrated the TF from S. moellendorffii exerted its anti-gout activity by inhibiting the NLRP3/ASC/Caspase-1 pathway." (PMID 34079466, 2021). "The enhanced production of mature IL-1β by gout PBMCs was shown to likely be due to enhanced caspase-1 mediated conversion of pro-IL-1β." (PMID 34992596, 2021). "Active caspase-1 catalyzes the conversion of pro-interleukin-1 beta (pro-IL-1β) to mature IL-1β, which is the primary effector pro-inflammatory cytokine in gout." (PMID 34992596, 2021). "Activation of caspase-1 is the main characteristic of inflammasome activation, with higher caspase-1 serum level in SpA, gout, inflammatory arthritis, and osteoarthritis than in other conditions." (PMID 34692718, 2021). "Meanwhile, these effects were predominantly reversed through the pretreatment with BRD4 inhibitor JQ-1, suggesting its involvement of Caspase-1-dependent pyroptotic cell death in mechanisms of acute gouty arthritis." (PMID 33162822, 2020). "MSU crystals engage the Nlrp3 inflammasome, leading to the activation of caspase-1 and production of IL-1β and IL-18 within gout-affected joints, promoting the influx of neutrophils and monocytes." (PMID 31803174, 2019). "Caspase-1 and NLRP3 are closely linked to the pathogenesis of various metabolic diseases including gouty arthritis." (PMID 31871475, 2019). "A ‘younger’ gut microbiota could suppress the activation of NLRP3, caspase-1, and IL-1β, thereby reducing the inflammatory response in gout." (PMID 39907694, 2025). "Active caspase-1 is well recognized to cleave pro-IL-1β to produce mature IL-1β in the process of NLRP3 inflammasome activation, which is considered a pathogenic mechanism in the pathogenesis of gout." (PMID 39065733, 2024). "Interestingly, LXA4 also significantly inhibited the expression of NLRP3, cleaved caspase-1, and matured IL-1β in the joint of gouty arthritis rats." (PMID 36569930, 2022). "Moreover, LXA4 alleviated joint inflammation and decreased the production of cleaved caspase-1 and matured IL-1β in gouty arthritis rats." (PMID 36569930, 2022). "Although it is widely accepted that gout is an inflammatory disease characterized by urate crystal-induced NLRP3 inflammasome activation with up-regulated caspase-1 protease and IL-1β in macrophages, recent evidence has highlighted that serum IL-17 levels are significantly elevated in gout patients." (PMID 35197978, 2022). "Furthermore, βOHB improved NLRP3 inflammasome-mediated inflammatory diseases, such as Muckle-Wells syndrome, spinal cord injury, and gout flares, and reduced caspase-1 activation and IL-1β secretion." (PMID 35585627, 2022). "Furthermore, in a mouse gout model by intraarticular MSU injection, mice deficient in NLRP3, caspase-1, or ASC showed much reduced pain response as well as reduced neutrophil infiltration and IL-1β in ankle joints." (PMID 33785039, 2021). "Similarly, freshly isolated synovial fluid cells (SFCs) from five gout patients were incubated with the presence of Eri, and caspase-1 activation and IL-1β production were inhibited in all patients." (PMID 34745110, 2021). "The leucine-rich region located at the C-terminus of the NLRP3 molecule can recognize the endogenous danger signals caused by MSU, and then MSU combines with NLRP3 to promote the activation of NLRP3 inflammasomes and drive caspase-1 to process pro-IL-1β into mature IL-1β, which leads to gout flare." (PMID 33935726, 2021).
gout (continued). "Therefore, the results indicated that TF alleviated LPS/MSU induced cellular gout model via regulation of NLRP3/ASC/Caspase-1 signaling pathway." (PMID 34079466, 2021). "Considering the connection between IL-1β and Caspase-1, flow cytometry was used to investigate whether BRD4 inhibitor have an impact on Caspase-1-dependent pyroptosis in animal model of gouty arthritis." (PMID 33162822, 2020). "Additionally, many reports have focused on the role of caspase-1 in gout; however, little is known to date about the role of caspase-11 in this sterile, inflammatory disease condition." (PMID 31803174, 2019). "Indeed, the oral administration of sulforaphane dose-dependently attenuated foot swelling and neutrophil recruitment while decreasing foot Il-1β levels and caspase-1 activity in animals with acute gout induced by MSU and air pouch." (PMID 31200447, 2019). "Among these pathways and genes, NOD-like receptor signaling pathway may play an important role in the curative effect of JSCBR on gouty arthritis by regulation of NRLP3/ASC/CASP1/IL1B." (PMID 32082152, 2019). "Recent study showed that CASP1 played a key role in the course of gout." (PMID 26557856, 2015). "This association of PI3K with gout was further confirmed on a murine model of gout which elucidated that PI3Kγ is crucial for MSU crystal–induced acute joint inflammation and for mediating neutrophil migration and activation in gout through the regulation of caspase-1 activation." (PMID 38042879, 2023). "However, there was no study reporting the role of CASP1 gene transcript variant in different traditional Chinese medicine (TCM) syndromes of primary gout yet." (PMID 26557856, 2015). "The previous study also demonstrated that circHipk3 accelerates the production of CASP1 and NLRP3 in macrophages in gouty arthritis." (PMID 39601144, 2024). "In mouse BMDMs, ER can specifically inhibit the activation of caspase-1 and the secretion of IL-1β by inhibiting ASC oligomerization, suggesting its potential as a treatment for HUA and gout." (PMID 38708084, 2024). "The results showed that the expression of NLRP3 and active caspase-1 p20 was elevated in HFD/PO-induced HUA and MSU-induced gouty arthritis mouse models." (PMID 38708084, 2024). "Recent in vivo and in vitro studies on a small molecule caspase-1 inhibitor, NSC697923, showed its effectiveness in an animal model of gouty arthritis." (PMID 37445927, 2023). "NLRP3 inflammasomes activate IL-1β by activating caspase-1 and then activate the NOD receptor family signaling pathway to induce gout inflammation." (PMID 35449811, 2022). "Extracellular ATP is a signaling molecule that acts on P2X7R to activate the NLRP3-caspase-1-IL-1β signaling pathway, aggravating MSU crystal-induced gout pathogenesis." (PMID 36052144, 2022). "As a clinical drug for gouty arthritis treatment, colchicine (COL) can suppress the activation of caspase-1 and prevent the release of IL-1β and IL-18, thereby inhibiting the occurrence of gouty arthritis." (PMID 36297105, 2022). "The protein expression levels of inflammasome components (ASC, caspase-1, and NLRP3) in ankle synovial tissues of MSU-induced gout rats were measured by immunohistochemistry." (PMID 31590257, 2019). "In mouse gouty arthritis models, oral administration of CAPE suppressed MSU crystals-induced caspase-1 activation and IL-1β production in the air pouch exudates and the foot tissues, correlating with attenuation of inflammatory symptoms." (PMID 27934918, 2016). "In addition, to verify the role of IL-37 in gout, THP-1 macrophages stimulated with recombinant IL-37 dose-dependently suppressed the activation of caspase-1 and IL-1β in MSU-induced inflammation." (PMID 39065733, 2024). "As predicted, gout synovial fluid served as an excellent positive control, because the inflammatory response to monosodium urate crystals leads to a NLRP3 inflammasome formation, caspase-1 activation and IL-1β release." (PMID 36936231, 2023).
gout (continued). "NLRP3 inflammasome produces IL-1β in gout, composed of NLRP3, ASC, and pro-caspase-1." (PMID 37881185, 2023). "For example, the most highly cited study published in Nature showed that MSU engaged the caspase-1-activating NALP3 inflammasome, resulting in the production of active interleukin (IL)-1beta and IL-18, which had a profound impact on the study of gout flare mechanism and targeted therapy." (PMID 35844867, 2022). "Importantly, we have demonstrated that wedelolactone indeed suppressed caspase 1 (p20) and IL‐1β expression in MSU‐induced gouty arthritis." (PMID 32656909, 2020). "Our results showed that gallic acid could reduce leukocyte infiltration, the expression of IL-1β and caspase 1 (p20) in joint tissues, as well as relieve inflammation in MSU-triggered gouty arthritis." (PMID 33365024, 2020). "Therefore, cardamonin could reduce the level of NLRP3, caspase 1, IL-1β, and COX-2 under MSU stimulation, which might help for gout treatment." (PMID 34577821, 2021). "Simiao decoction and its related FMT significantly reduced the production of NLRP3, caspase-1 and ASC, but allopurinol only reduced the production of ASC, and its related FMT had no significant influence on NLRP3 inflammasome in gouty arthritis mice." (PMID 37344836, 2023).
viral infection (68 papers, 2009 to 2026). "This phenomenon is consistent with viral diseases and macrophage damage caused by myoglobin, which is likely attributed to caspase-1 and RIG-I having structurally identical CARD regions." (PMID 40175216, 2025). "Caspase-1 mRNA expression was assessed, and the results indicate that it was upregulated in vitro or in vivo and that it had a dose-dependent association with viral infection in LMH cells." (PMID 37063902, 2023). "This was further confirmed by western blot analysis showing that NLRP3 deficiency blocked the secretion of mature IL-1β and caspase-1 in supernatant of Park2−/− cells after viral infection." (PMID 31229895, 2019). "Therefore, PLD1 participates in bacterial and viral infectious diseases; however, the mechanism underlying the Vu0155069 effect on caspase-1 activity is unclear." (PMID 37381714, 2023). "Many studies have implicated caspase-1 in virus infection-associated inflammasome activation." (PMID 36503883, 2022). "These suggest that the production of NLRP3 inflammasome and its downstream effectors, caspase-1 and IL-1β, is positively correlated with the duration of viral infection." (PMID 40284982, 2025). "Inflammasome activation plays a role in the host defence against viral infection, whereby it activates caspase-1 and initiates the release of IL-1β." (PMID 38890537, 2024). "Inflammasomes were also enhanced by viral infection, as indicated by immunoblotting for mature IL-1β and cleaved caspase-1 P20." (PMID 38989466, 2024). "We demonstrated that viral infection induces cleavage of GSDMD by increasing cleaved caspase-1 levels, and AZ has been shown to inhibit this process." (PMID 38247540, 2024). "PRV VP22 disrupts the binding between ZBP1 and RIPK3/Caspase-8 and inhibits the cleavage of Caspase-1 and IL-1β induction, thereby promoting viral infection." (PMID 39475237, 2024). "Together, these results suggest that pyroptosis is involved in the pathogenesis of viral infections and that treatment with a caspase-1 inhibitor is beneficial to the host response against viral infection." (PMID 36629424, 2023). "Numerous studies have demonstrated significant inflammasome activity in viral infection models, including the activation of caspase-1 and the secretion of interleukin-1β (IL-1β)." (PMID 37704783, 2023). "The AIM2 gene is related to the hyperinflammatory manifestation of MIS-C patients since triggers caspase-1 and unleashes pro-inflammatory cytokines such as IL-1β and IL-18,19 which are also involved in the innate immune response to viral infections." (PMID 35770252, 2022). "To confirm the mechanism for pyroptosis that occurred in macrophages infected with ZIKV, we chose to use Belnacasan, or VX-765, a specific caspase-1 inhibitor to pre-treat the cells prior to viral infection." (PMID 35446851, 2022). "During viral infection, pro-IL-1β is cleaved by inflammasome-derived caspase-1 and become a mature product." (PMID 35464987, 2022). "Another related inflammasome—the AIM2 inflammasome, composed of AIM2, ASC, and Casp1 subunits—was activated by cytosolic DNA during bacterial and viral infection." (PMID 32069862, 2020). "In the field of HIV, 95% quiescent lymphoid CD4+T cells died of caspase-1-mediated pyroptosis triggered by abortive viral infection and blocking CD4+T cell pyroptosis was considered a potential “anti-AIDS” therapy." (PMID 32258157, 2020). "In our study, we first demonstrated that virus infection leads to pyroptosis by measuring activation of caspase-1 and IL-1β in human macrophages infected with MERS-CoV." (PMID 30634407, 2019). "Both gut microbiota and viral infections are able to activate caspase-1 through canonical inflammasomes." (PMID 31492850, 2019). "Both cytokines were markedly elevated at the early phase of EV71 replication (at 6 h p.i.), corresponding to the rapid increase of caspase-1 in response to viral infection." (PMID 29440739, 2018).